CTBP2 (C-terminal binding protein 2)
Diseases named in the same sentence as CTBP2 in open-access papers (continued):
Sharing a sentence is not in itself a finding about the gene and the disease.
tumor (continued). "CircHERC4 exerts critical roles in promoting tumor aggressiveness through miR-556-5p/CTBP2/E-cadherin pathway and is a prognostic biomarker of the disease, suggesting that circHERC4 may serve as an exploitable therapeutic target for patients with CRC." (PMID 34781990, 2021). "The results of xenograft subcutaneous suggested that overexpression of circHERC4 could accelerate tumor growth and this effect could be inhibited after CTBP2 siRNA or miR-556-5p mimic was injected." (PMID 34781990, 2021). "CtBP2’s role in driving a tumor initiating cell (TIC) niche in solid tumors is emerging." (PMID 30197752, 2018). "This mislocalization could explain the profound effect of Ctbp2 haploinsufficiency on polyp number and survival in Apcmin mice and supports further therapeutic development of CtBP as a target in APC mutated neoplasia." (PMID 30197752, 2018). "C-terminal binding protein-2 (CtBP2) is a known transcriptional corepressor and modulator of several essential cellular processes, and it has also been shown to activate tumorigenesis and tumor progression." (PMID 28404932, 2017). "In addition, the proportion of p16INK4A-positive tumor cells was negatively correlated with the proportion of CtBP2-positive and Ki-67-positive tumor cells." (PMID 28412731, 2017). "The in vivo animal model confirmed that CtBP2 promotes the tumor growth." (PMID 28412731, 2017). "Based on these results, it is tempting to speculate that tumor cells with stabilized CtBP2 expression are selected for over time, because of their ability to overcome impaired self-renewal imposed on stem cells by oncogenic stress conditions such as DNA damage or proteotoxicity." (PMID 33972635, 2021). "However, whether HGSOC tumor progression is dependent on CtBP2 or its paralog CtBP1, is not well understood." (PMID 32332713, 2020). "However, CTBP2 was discarded after manual inspection with Integrative Genomics Viewer (IGV), because multiple mutations were detected from a single read of CTBP2 in both tumor and normal samples, probably due to mapping error." (PMID 29731965, 2018). "An increasing body of evidence indicates that CtBP2 is involved in tumorigenesis and tumor progression by the regulation of several essential cellular processes, such as transcriptional repression, and is correlated with poor prognosis in a number of tumor types." (PMID 28412731, 2017). "To validate the role of spatial location within the tumor mass in the relationship between CYR61 and CtBP2 expression levels, we established larger 3D spheroids." (PMID 40038783, 2025). "CtBP2 is likewise frequently overexpressed in CRC and enriched in tumor-initiating cell (TIC) populations." (PMID 41419197, 2025). "In particular, C-terminal Binding Protein 2 (CTBP2), an OCT1/AR target gene, was correlated with poor prognosis and immunosuppressive effects in the tumor microenvironment." (PMID 38698344, 2024). "In conclusion, our studies demonstrated that both PCIF1 and CTBP2 were independent predictors in patients with HNSCC, and patients with increased nuclear expression of PCIF1 and CTBP2 in tumor lesions tended to have an unfavorable prognosis." (PMID 37643007, 2023). "We further demonstrated that CtBP2 haploinsufficiency reduced tumor initiating cell (TIC) abundance in APCmin/+ intestines, suggesting the oncogenic role of CtBP2 in intestinal neoplasia relates to its promotion of TIC activities." (PMID 32332713, 2020). "CtBP2 induces the epithelial-to-mesenchymal transition (EMT), helps to repress a number of tumor suppressors (e.g., E-cadherin, PTEN, Ink4 family tumor suppressors), and functions as an antagonist of apoptosis." (PMID 28404932, 2017). "In all tumor types, differentially methylated CpGs were highly enriched in binding sites of polycomb-related SUZ12, EZH2 and CTBP2, and the enrichment rate strongly correlated with the degree of CGI methylation." (PMID 26464434, 2016).
tumor (continued). "Based on these findings, we hypothesized that the CtBP2-G9a interaction cooperates to drive CRC progression and that pharmacological or genetic disruption of this interface may restore tumor-suppressor gene expression and attenuate malignant proliferation." (PMID 41419197, 2025). "An increased expression of CtBP2, but not CtBP1, was reported in a small cohort of tumor tissue samples (n = 28) compared to noncancerous bone tissue samples." (PMID 40038783, 2025). "In this report, we have used a cell line derived from a CKP mouse PDAC tumor in which we homozygously deleted the Ctbp2 gene via CRISPR, to further interrogate the oncogenic mechanism of action of Ctbp2 in PDAC progression using an orthotopic allograft PDAC mouse model." (PMID 37949862, 2023). "The results revealed that the double knockout of PCIF1 and CTBP2 did not exhibit substantial alterations in the tumor cell phenotype compared with the sole knockout of PCIF1." (PMID 37643007, 2023). "Further mechanism research suggested that miR-556-5p could act as a tumor suppressor in CRC via post-transcriptional inhibition of its target gene, C-terminal-binding protein 2 (CTBP2)." (PMID 34781990, 2021). "Moreover, therapeutic targeting of CtBP2 in CKP mice with the small-molecule CtBP inhibitor 4-Cl-HIPP, resulted in reduced tumor burden similar to that induced by standard gemcitabine, with the combination synergistically attenuating tumor growth." (PMID 31586042, 2019). "Importantly, disruption of this protein-protein interface—either by genetic deletion of the G9a pre-SET motif or by CtBP2 monomerization—abolished CtBP2-mediated stimulation of G9a, restored PTEN expression, and impaired tumor cell fitness, consistent with our functional data." (PMID 41419197, 2025). "The tumor grade of Ctbp2-cKO HNSCC was not as advanced as compared with the control." (PMID 37643007, 2023). "CTBP2 mRNA level was overexpressed in tumor tissues compared to adjacent non-cancerous tissues." (PMID 34781990, 2021). "A small-molecule inhibitor of CtBP2, 4-chloro-hydroxyimino phenylpyruvate (4-Cl-HIPP) phenocopied Ctbp2 deletion, decreasing tumor burden similarly to gemcitabine, and the combination of 4-Cl-HIPP and gemcitabine further synergistically suppressed tumor growth." (PMID 31586042, 2019). "Thus, we hypothesized that declined miR-101 expression in human KLRG1+ T cells leaded to elevated expression of co-repressor CtBP2, which subsequently suppressed the effector cytokine production of KLRG1+ T cells, resulting in impaired T cell antitumor immunity in tumor microenvironment." (PMID 27557510, 2016).
metabolic disease (4 papers, 2021 to 2025). A congenital disorder (due to inherited enzyme abnormality) or acquired (due to failure of a metabolically important organ) disorder resulting from an abnormal metabolic process. "Intriguingly, CtBP2 was also recruited into genomic loci encoding gluconeogenetic genes and inflammatory genes, critical for the pathogenesis of metabolic diseases." (PMID 34728642, 2021). "All of them indicated that the acute CtBP2 upregulation was the upstream event after the blast, which then led to astrocyte proliferation and metabolic disorders." (PMID 37763802, 2023). "Our findings support a central role of CtBP2 in global hepatic metabolic control and an exciting therapeutic potential of targeting this mechanism in metabolic diseases." (PMID 34728642, 2021).
brain disorder (1 paper, 2024). A disease affecting the brain or part of the brain. "We found 7 variants that were associated with neurodevelopment and brain disorders, of which, 4 variants were found in both patients, namely in genes CTBP2, CDC27, UNC13D and IRF8, and 3 variants found in either of the patients, NDUFAF3, MRPS25, MORC3." (PMID 38638145, 2024).
infection (1 paper, 2014). The state of being infected such as from the introduction of a foreign agent such as serum, vaccine, antigenic substance or organism. "We also determined the effects of endogenous CtBP1 and CtBP2 on the E2F1 promoter activity by using A549 cells that were acutely depleted of both CtBP1 and CtBP2 by infection with lentiviral vectors that express shRNAs against CtBP1 and CtBP2 followed by short term drug selection." (PMID 24955216, 2014).
respiratory disease (1 paper, 2019). "In Chinese Erhualian pigs, QTLs affecting respiratory disease were identified by a genome-wide association study; CXCL6, CXCL8, KIT, and CTBP2 were highlighted as candidates that might associated with resistance or susceptibility to swine enzootic pneumonia-like respiratory disease." (PMID 31656701, 2019).
CTBP2 also shares sentences with these, for which no sentence is quoted: chronic renal failure (2 papers); esophageal cancer (2); liver cancer (2); pancreatic adenocarcinoma (2); acute myeloid leukemia (1); acute respiratory distress syndrome (1); adenocarcinoma (1); benign prostatic hyperplasia (1); cardiac hypertrophy (1); cataract (1); cervical cancer (1); cognitive disorder (1); colon adenocarcinoma (1); diabetic retinopathy (1); head and neck squamous cell carcinoma (1); Hip dysplasia (1); Immunodeficiency (1); Intellectual disability (1); intestinal cancer (1); intestinal disease (1); invasive ductal carcinoma (1); lens diseases (1); liver dysfunction (1); lymph node metastasis (1); melanoma (1); neurological disorders (1); night blindness (1); ovarian serous cystadenocarcinoma (1); ovarian tumors (1); prostate adenocarcinoma (1).
A further 3 diseases each share a sentence with CTBP2 in 1 paper.